TMPRSS2 (transmembrane serine protease 2)
Diseases named in the same sentence as TMPRSS2 in open-access papers (continued):
Sharing a sentence is not in itself a finding about the gene and the disease.
prostate carcinoma (continued). "There are examples of critical molecular events for cancer development, such as TMPRSS2–ERG fusions, the most frequent molecular alteration in prostate cancer occurring in about 50% of cases, which are completely unrelated to disease outcome." (PMID 34625909, 2022). "A recent study shows that ERG expressed by the TMPRSS2:ERG fusion gene can directly regulate both the α1 and β1 subunits of sGC and contribute to promote the downstream effector cGMP-PKG activity in prostate cancer cells." (PMID 35526071, 2022). "This was particularly curious since AR binding to TMPRSS2 and ERG introns promotes formation of the TMPRSS2/ERG gene rearrangement in prostate cancer." (PMID 34409300, 2021). "The TMPRSS2-ERG genomic rearrangement can be detected in post-DRE urine samples with a specificity of 93% and a positive predictive value of 94% for prostate cancer diagnosis." (PMID 34026653, 2021). "The protease TMPRSS2 has only been studied in zebrafish in its rearranged form TMPRSS2-ERG, a biomarker of prostate cancer." (PMID 33952614, 2021). "For example, when AR drives expression of ERG from the common TMPRSS2:ERG fusion, both of these factors have been recently described to be involved in the regulation of long non-coding RNAs (lncRNAs) in prostate cancer." (PMID 33634124, 2021). "In prostate cancer, the ETS family members ERG as well as ETV1 are commonly rearranged and ectopic ERG expression by TMPRSS2-ERG fusion blocks NE differentiation." (PMID 34121659, 2021). "Ectropic expression of TMPRSS2–ERG fusion was found to be not only involved in alteration of chemo-sensitivity, but also in chemo-responsiveness to androgens in prostate cancer, depending on cell line and fusion type." (PMID 34399734, 2021). "These anti-androgen drugs have been shown to be effective and safe for the treatment of prostate cancer for decades, and are promising for mitigating symptom severity in patients with SARS-CoV-2 by downregulating TMPRSS2 levels." (PMID 34001144, 2021). "Consistently, enzalutamide significantly decreased TMPRSS2 expression and inhibited SARS-CoV-2 infection in human prostate cancer cells." (PMID 33558541, 2021). "Among these drugs, a second-generation antiandrogen agent, enzalutamide, was proposed because it reduces the expression of transmembrane serine protease 2 (TMPRSS2), a key component mediating SARS-CoV-2-driven entry, in prostate cancer cells." (PMID 33558541, 2021). "The TMPRSS2-ERG gene fusion is well recognized as a molecular sign of prostate cancer, as it occurs in over half of primary prostate cancer cases." (PMID 34001144, 2021). "Recurrent gene rearrangements involving the androgen-regulated transmembrane protease serine 2 (TMPRSS2) and ETS transcription factor, v-ets erythroblastosis virus E26 oncogene homolog (ERG) occur in ~50% of prostate cancer (PCa) patients." (PMID 34493733, 2021). "The hepatocyte growth factor (HGF)/c-Met cell is activated by TMPRSS2, provoking the survival pathway of HGF/c-Met receptor tyrosine kinase signaling and stimulating a pro-invasive role in prostate cancer cells." (PMID 34068970, 2021). "We also discuss the clinical relevance of especially the most common prostate cancer fusion gene TMPRSS2-ERG, as well as present open questions of prostate cancer fusions requiring further investigation." (PMID 33634124, 2021). "For TMPRSS2-ERG, a well-known fusion in prostate cancer, the chimeric mRNA is typically a consequence of two intragenic breakpoints; indeed, we found 25 such cases in our cohort." (PMID 32631391, 2020). "Recently, we demonstrate that the transcription factor ERG, expressed by the TMPRSS2:ERG fusion gene, can directly transactivate the ESRRA gene in advanced prostate cancer." (PMID 32226548, 2020). "Gene fusion between TMPRSS2 and members of the E26 transformation specific (ETS) transcription factor family (ERG or ETV) is another mechanism by which TMPRSS2 plays a role in prostate cancer progression." (PMID 32764454, 2020).
prostate carcinoma (continued). "Fusion of the TMPRSS2 and ERG (or the related ETV1) genes has been reported to occur in the majority of prostate cancers and is suggested to lead to an androgen‐dependent amplification of ETS‐regulated genes." (PMID 32358833, 2020). "The androgen-regulated TMPRSS2 promoters form a fusion gene with coding regions of the proto-oncogenic ETS transcription factor family members, which are closely related to prostate cancer and regulate many biological processes." (PMID 33193689, 2020). "The TMPRSS2:ERG fusion, which occurs in 40–50% of prostate cancer patients and results in ERG expression, is an early genomic event during tumor development." (PMID 32054861, 2020). "Confirming previous reports, the most recurrent case was TMPRSS2-ERG (n = 72), which was completely restricted to prostate cancer (n = 490 samples)." (PMID 33097743, 2020). "In LNCaP human prostate cancer cells, the PPARα (NR1C1) agonist fenofibrate was able to mitigate against the androgen receptor agonist‐evoked increase in TMPRSS2 expression." (PMID 32358833, 2020). "The known fusion CCDC170-ESR1 was found in three breast cancer samples while the well-described promoter substitution event, TMPRSS2-ERG, was identified in one prostate cancer cell line." (PMID 33097743, 2020). "Specifically, microRNAs such are miR-346 and miR-361-3p were suggested to modulate the expression of PSA, TMPRSS2 and DRG1 in prostate cancer." (PMID 33245732, 2020). "The Yegnasubramanian Prostate Cancer gene set is positively correlated with ALCAM and TMPRSS2 gene expression." (PMID 32899474, 2020). "During gene fusion, the 5′-untranslated region of TMPRSS2 is merged with the transcription factors, ERG or ETV genes which enhance prostate cancer progression and invasion." (PMID 32764454, 2020). "On the other hand, TMPRSS2 plays a major role in SARS-CoV-2 cell entry and is coincidentally dysregulated in prostate cancer." (PMID 32974166, 2020). "TMPRSS2 protein, utilized by SARS-CoV-2 for S protein priming is highly expressed in normal prostate epithelial and prostate cancer cells." (PMID 32974166, 2020). "In the present study, we examined the structural preconditions for TMPRSS2-ERG fusion sites in comparison with mesenchymal tumors in pediatric patients to determine whether the sequence composition is suitable for the establishment of tumor-specific quantification assays in prostate cancer patients." (PMID 31915468, 2019). "Although fusion of the AR regulated TMPRSS2 promoter to ETS related gene (ERG) that results in ERG overexpression is a common event in CA prostate cancer patients (50–70%), it is less frequent among AA and other ethnic groups." (PMID 31741711, 2019). "Androgen receptor (AR) signaling has been shown to bring the androgen regulated gene TMPRSS2 and the ERG gene in close proximity in prostate cancer cell line models." (PMID 31106278, 2019). "A recent study has provided evidence that the TMPRSS2-ERG fusion protein blocks neuroendocrine and luminal cell differentiation to maintain prostate cancer proliferation." (PMID 31366128, 2019). "Fusion of the TMPRSS2 and ERG genes is the most prevalent gene fusion in prostate cancer, occurring in about 50% the cases." (PMID 30664691, 2019). "TMPRSS2-ERG is the frequent ERG gene rearrangement observed in prostate cancer and SLC45A3 is the second most common ERG partner in prostate cancer and in most of patients SLC45A3-ERG rearrangements co-occur with TMPRSS2-ERG rearrangements." (PMID 31366128, 2019). "The genomic rearrangements leading to the fusion of the AR-regulated TMPRSS2 gene promoter and the N-terminally deleted ERG coding sequence represents the most common prostate cancer-specific driver gene alteration." (PMID 31013716, 2019).
prostate carcinoma (continued). "Similar spatial proximity during interphase has been proposed to mediate RET and H4 fusion in papillary thyroid carcinoma, and TMPRSS2 and ERG in prostate cancer." (PMID 31007851, 2019). "The expression of TMPRSS2—which provides the promoter for the TMPRSS2-ERG fusion, presents in about 50% of organ-confined prostate cancers, the commonest genetic abnormality in prostate cancer, is strongly regulated by RME." (PMID 31108832, 2019). "The overexpression of ERG, in a majority of prostate cancers, is driven by this fusion event, which switches ERG to fall under the control of the androgen-driven promotor of the TMPRSS2 gene." (PMID 31275657, 2019). "In prostate cancer, the ERG gene is frequently translocated to the TMPRSS2 promoter region, with the resulting TMPRSS2-ERG fusion protein expressed in ~50% of human prostate cancers." (PMID 30733438, 2019). "Only the second study of its kind for the African continent, we support a link between TMPRSS2‐ERG status and prostate cancer racial health disparity beyond the borders of the United States." (PMID 31090091, 2019). "TMPRSS2-ERG fusion can block XRCC4-mediated NHEJ by inhibiting DNA-PKcs auto/trans-phosphorylation and thus sensitizes prostate cancer cells to PARP inhibition." (PMID 31007851, 2019). "Transcript analysis of additional prototypical AR‐regulated genes FKBP5, KLK2, NKX3.1, and TMPRSS2 shows a similar pattern of expression to PSA and Ki67, indicating general inhibition of androgen signaling by bicalutamide in prostate cancer PDEs." (PMID 30117261, 2018). "Among these fusion genes, TMPRSS2:ERG (T:E) fusion is the most dominant rearrangement and prevalent in majority of prostate cancer patients (40–70%)." (PMID 30042415, 2018). "SeqOthello extracted 122 pre-identified occurrences of TMPRSS2-ERG and 142 novel occurrences, all from prostate cancer samples." (PMID 30340508, 2018). "Article sets for ‘TMPRSS2:ERG or ETS-related gene’ and ‘prostate cancer’ were generated and compared (1 March 2017) using 867 and 138 391 articles, respectively." (PMID 29342271, 2018). "In this study, we made the unexpected observation that AR protein levels, but not transcript levels, as well as the protein and transcript levels of AR-activated targets PSA and TMPRSS2, were decreased by depletion of BMI1 in AR-positive prostate cancer cells." (PMID 29402932, 2018). "We have further shown that TMPRSS2-ERG fusion transcripts are expressed in 15 out of 25 prostate tumors, consistent with the notion that TMPRSS2-ERG fusion transcripts are prostate cancer biomarkers." (PMID 28881586, 2017). "Although, TMPRSS2-ERG overexpression has high prostate cancer specificity, its role in detecting aggressive prostate cancer is still controversial." (PMID 28061466, 2017). "The most common TMPRSS2:ETS fusion is TMPRSS2:ERG; this fusion promotes growth in prostate cancer cells, in mouse prostate, and in xenograft models." (PMID 28591703, 2017). "In prostate cancer patients, the presence of two well-known biomarkers in exosomes recovered from urine samples, such as the PCA-3 and TMPRSS2:ERG mRNAs, indicated an alternative strategy for early screening of the disease." (PMID 28098821, 2017). "TMPRSS2-ERG is a fusion transcript that emerges as prostate cancer cells specific biomarker; when overexpressed, it plays a pivotal role in prostate cancer transformation, EMT and invasion." (PMID 28430640, 2017). "On the other hand, chromosomal rearrangements between TMPRSS2 and ERG (TMPRSS2:ERG), made by AR binding to the “breakpoint ARE” in this region, occur in around 50% of prostate cancers." (PMID 28264478, 2017). "Chromosomal rearrangements between the androgen-regulated gene, TMPRSS2, and the oncogenic ETS transcription factor gene, ERG, occurs in approximately 30–50% of prostate cancers (PRAD)." (PMID 29299133, 2017). "Ultimately, genomic testing revealed a TMPRSS2-ERG fusion in the SCC, which is characteristic of prostate cancer." (PMID 28423702, 2017).
prostate carcinoma (continued). "In terms of TMPRSS2:ERG, we previously developed a PI polyamide targeting a common sequence in AR-related DNA break points among TMPRSS2 and ERG gene loci to repress TMPRSS2:ERG expression and prostate cancer cell growth." (PMID 28264478, 2017). "The data show substantial heterogeneity for MAP3K7 deletion in prostate cancer and suggest that MAP3K7 deletion largely prevents development of TMPRSS2:ERG fusions." (PMID 26684029, 2016). "ERG is a transcription factor, which becomes expressed as a result of a gene fusion involving the androgen-regulated gene TMPRSS2 and the ERG locus in about 50% of prostate cancers." (PMID 27861151, 2016). "Nilsson was able to detect two known prostate cancer biomarkers, PCA3 and TMPRSS2-ERG, in exosomes isolated from urine of prostate cancer patients, first showing their potential for prostate cancer diagnostics." (PMID 27305142, 2016). "We used immunohistochemistry on each patient specimen to determine the expression of proteins that frequently undergo alteration in prostate cancer, including PTEN, TMPRSS2-ERG, MYC and Nkx3.1." (PMID 27351281, 2016). "Genomic fusion between the membrane-bound serine protease TMPRSS2 and the ETS-family transcription factor ERG is an early genetic alteration occurring in ~50% of prostate cancers." (PMID 27536883, 2016). "Experimental data also suggest that the increased transcriptional activity favors the formation of TMPRSS2:ERG, a fusion gene found in about 50% of prostate cancers." (PMID 26421011, 2015). "Several promising biomarkers for male infertility and prostate cancer include ECM1, TEX101, LDHC, TKTL and ACPP proteins, and prostate specific antigen (PSA), TMPRSS2-ETS." (PMID 26097523, 2015). "Recently, fusions involving SKIL (which encodes a SMAD inhibitor) 3′ to androgen-regulated promoters such as TMPRSS2, SLC45A3, and ACPP, were found in 6 of 540 (1.1 %) prostate cancers and one cell line xenograft, LuCaP-77." (PMID 26684754, 2015). "Gene fusions involving ETS family transcription factors (mainly TMPRSS2-ERG and TMPRSS2-ETV1 fusions) have been found in ~50% of human prostate cancer cases." (PMID 25780911, 2015). "Gene fusions involving the androgen-regulated gene TMPRSS2 and ERG occur in about 50% of prostate cancers and result in strong ERG protein overexpression with consequent deregulation of the expression of a large number of genes." (PMID 25825985, 2015). "Sequencing-based genomic abnormality analysis revealed locus-specific gains or losses that were common in prostate cancer, such as 8q gains, AR amplifications, PTEN losses and TMPRSS2-ERG fusions." (PMID 25915538, 2015). "Conversely, some lineage-specific genes are seen to serve as 5′ partners across multiple different 3′ genes; for example, TMPRSS2 and SLC45A3 in prostate cancer have been observed as 5′ partners of ERG, ETV1, ETV4, ETV5, BRAF, and ELK4." (PMID 26684754, 2015). "Detection of TMPRSS2-ERG in circulating tumor cells in therapy-naive patients and in castration-resistant prostate cancer patients following treatment suggests potential applications in non-invasive monitoring of the therapeutic response." (PMID 26684754, 2015). "The discovery of fusion transcripts involving ERG coding sequences and TMPRSS2 promoter sequences has elucidated a role for ERG in the initiation and progression of prostate cancer in a subset of patients." (PMID 25889691, 2015). "We treated prostate cancer cells with these inhibitors to determine their impacts on AR signaling by measuring AR targeted transcription of PSA, TMPRSS2 and FKBP5 genes." (PMID 26009876, 2015). "In 2009, Nilsson and coworkers demonstrated the presence of two known prostate cancer biomarkers, PCA-3 and TMPRSS2:ERG, in exosomes isolated from the urine of prostate cancer patients." (PMID 25695100, 2015). "Gene fusions between the TMPRSS2 5’-untranslated region and the ERG oncogene are found in approximately half of prostate cancer cases." (PMID 26571387, 2015).
prostate carcinoma (continued). "One such example, found in 50 % of prostate cancers, involves the fusion between the ETS transcription factor ERG with the androgen-regulated gene TMPRSS2, resulting in overexpression of ERG in the prostate epithelium." (PMID 26310325, 2015). "The most prevalent gene fusion is the TMPRSS2-ERG, present in nearly half of all human prostate cancers, followed by rearrangements involving the ETV1, ETV4, ETV5 and FLI1 genes, often with promoter fusion partners other than TMPRSS2." (PMID 25595908, 2015). "We recently reported mouse models of prostate cancer that recapitulate the most frequent ETS gene fusions, TMPRSS2-ERG and TMPRSS2-ETV1, with ectopic ERG or ETV1 expression from the endogenous Tmprss2 promoter." (PMID 25780911, 2015). "Recurrent gene fusion between the androgen-regulated gene TMPRSS2 and members of the ETS transcription factor family, most commonly ERG, are present in about 50% of prostate cancer cases." (PMID 24505269, 2014). "Recently, the potential prostate cancer biomarkers, such as prostate cancer antigen 3 (PCA3), TMPRSS2-ERG gene fusions and p501s (prostein), were investigated as auxiliary diagnosis candidates for prostate cancer." (PMID 24571686, 2014). "It is worth noting that the TMPRSS2-ETS fusion genes, commonly detected in approx-imately 50% human prostate cancers, are positively regulated by AR." (PMID 24508459, 2014). "Detection of TMPRSS2-ERG fusion in urine was reported to yield >90% specificity and 94% positive predictive value in prostate cancer detection." (PMID 27351008, 2014). "Inhibitory effects of TMPRSS2-ERG8 on TMPRSS2- ERG3 were also corroborated by gene expression data from human prostate cancers, which showed a positive correlation between C-MYC expression and TMPRSS2-ERG3/TMPRSS2- ERG8 ratio." (PMID 25221645, 2014). "Noninvasive detection of TMPRSS2-ERG transcripts is possible in urinary sediments through real-time PCR, presenting a 93% specificity for prostate cancer." (PMID 24877145, 2014). "Recent improvements have been made in the visualization and quantification of the components of TMPRSS2-ERG signaling network, thus providing a better picture of different signaling pathways in TMPRSS2-ERG positive prostate cancer cells." (PMID 24739220, 2014). "With the landmark identification of a recurrent gene fusion event on chromosome 21 between the TMPRSS2 and ERG genes, prostate cancers are now categorized as "fusion-positive" and "fusion-negative"." (PMID 24739220, 2014). "The fusion between androgen regulated TMPRSS2 and ERG genes is present in ~50% of prostate cancer patients in Western countries." (PMID 25221645, 2014). "In contrast, cancers such as chronic myeloid leukemia and prostate cancer can be stratified by a cancer type-specific fusion such as BCR-ABL and TMPRSS2-ERG respectively." (PMID 24675677, 2014). "Chromosomal aberrations harboring a fusion product of ERG to form FUS/TLS-ERG in acute myeloid leukemia (AML), ERG-EWS in Ewing's sarcoma, or TMPRSS2-ERG in prostate cancers are predictive of poor prognosis." (PMID 24504051, 2014). "ERα-mediated regulation of oncogenic TMPRSS2-ERG fusion and oestrogen regulation of the EBAG9 gene, which confirms aggressive behaviour of prostate cancer, are noted examples that suggest a functional ERα-signalling pathway exists in prostate cancer." (PMID 25415230, 2014). "Proof that this form of analysis can provide disease- relevant findings comes from the identification of the fusion of TMPRSS2 and ETS transcription factor genes in prostate cancer through the use of the COPA software." (PMID 24416128, 2014). "Leshem and colleagues (2011) found that the promoter region of IL1R2 possesses putative binding motifs for the TMPRSS2/ERG fusion gene, which is highly expressed in aggressive prostate cancer." (PMID 24359571, 2013).